TBC1D17 (TBC1 domain family member 17)
Description:
Probable RAB GTPase-activating protein that inhibits RAB8A/B function. Reduces Rab8 recruitment to tubules emanating from the endocytic recycling compartment (ERC) and inhibits Rab8-mediated endocytic trafficking, such as that of transferrin receptor (TfR). Involved in regulation of autophagy.
Synonyms: FLJ12168
Tractability: PROTAC: ubiquitination databases record sites on it; its protein half-life has been measured.
Gene: Protein-coding gene on chromosome 19 (49,877,501 to 49,888,751, forward strand). Ensembl gene ENSG00000104946.
Subcellular location: Cytoplasmic vesicle, autophagosome; Cytoplasm; Recycling endosome
Pathways (Reactome):
Vesicle-mediated transport: TBC/RABGAPs
Gene Ontology:
Molecular function: protein binding; GTPase activator activity
Biological process: regulation of cilium assembly; retrograde transport, endosome to Golgi
Cellular component: cytoplasm; cytosol; recycling endosome; autophagosome
Genetic constraint (gnomAD): Loss-of-function variants: 68 observed, 74.82 expected, observed/expected ratio (o/e) 0.91, 90% interval 0.75 to 1.11. The synonymous counts are far from expectation, so gnomAD's model fits this gene poorly and the ratio says little. Missense variants: 935 observed, 812.28 expected, observed/expected ratio (o/e) 1.15, 90% interval 1.09 to 1.22. Synonymous variants: 452 observed, 346.37 expected, observed/expected ratio (o/e) 1.3, 90% interval 1.21 to 1.41.
Homologues: Orthologues: chimpanzee TBC1D17 (99% identical), macaque TBC1D17 (99% identical), dog TBC1D17 (93% identical), pig TBC1D17 (93% identical), guinea pig TBC1D17 (92% identical), rat Tbc1d17 (90% identical), mouse Tbc1d17 (89% identical), tropical clawed frog tbc1d17 (64% identical), zebrafish tbc1d17 (55% identical). Paralogues in human: TBC1D15 (48% identical), TBC1D16 (18% identical), TBC1D5 (16% identical), TBC1D9B (15% identical), TBC1D2B (15% identical), RABGAP1L (15% identical), TBC1D25 (15% identical), TBC1D1 (15% identical), TBC1D9 (15% identical), RABGAP1 (14% identical), TBC1D8 (14% identical), TBC1D2 (14% identical), and 33 more.
Diseases named in the same sentence as TBC1D17 in open-access papers:
TBC1D17 is named in the same sentence as 9 diseases in open-access papers, as found by Europe PMC text mining. Sharing a sentence is not in itself a finding about the gene and the disease. The quoted sentences say what the papers report.
ovarian carcinoma (2 papers, 2020 to 2022). A malignant neoplasm originating from the surface ovarian epithelium. "While it has been reported that TBC1D8 can regulated metabolic reprogramming to drive ovarian cancer progression, little research has been reported on TBC1D17 in cancer." (PMID 35918393, 2022). "Comparison of the MyoMed-946 and MyoMed-205 proteome data sets suggests that MyoMed-946-treated EDL may contain higher levels of Ttll12 (tubulin-tyrosine ligase-like protein 12) and Tbc1d17, both regulators of tubulin dynamics, correlating in ovarian cancers with a poor outcome." (PMID 33050629, 2020).
vitiligo (2 papers, 2023 to 2024). Generalized well circumscribed patches of leukoderma that are generally distributed over symmetric body locations and is due to autoimmune destruction of melanocytes. "Then, five mitophagy hub genes (GABARAPL2, SP1, USP8, RELA, and TBC1D17) were identified using two machine learning algorithms, and these genes showed high diagnostic specificity for vitiligo." (PMID 37287971, 2023). "The AUC values of hub genes were high in the combined dataset (GABARAPL2, AUC=0.988; USP8, AUC=0.94; RELA, AUC=0.927; SP1, AUC=0.894; and TBC1D17, AUC=0.927), implying that the five hub genes have high specificity for vitiligo and could be used as vitiligo diagnostic biomarkers." (PMID 37287971, 2023). "The results showed elevated GABARAPL2 and USP8 and decreased RELA, SP1, and TBC1D17 in vitiligo compared to healthy controls, which were consistent with bioinformatic analysis results." (PMID 37287971, 2023). "Through LASSO regression analysis and the random forest algorithm, we screened five mitophagy-related hub DEGs (GABARAPL2, USP8, RELA, SP1, and TBC1D17) in vitiligo." (PMID 37287971, 2023). "Furthermore, GABARAPL2, RELA, TBC1D17, and USP8, except of SP1, are implicated in cellular responses to stress and external stimuli; External stimuli, such as stress and oxidative stress, are vital factors in the etiology of vitiligo." (PMID 37287971, 2023). "Consistent with the bioinformatic analysis results, GABARAPL2 and USP8 mRNA levels were raised in vitiligo lesions, whereas the mRNA levels of RELA, TBC1D17, and SP1 were decreased." (PMID 37287971, 2023).
Stillbirth (1 paper, 2024). Death of the fetus in utero after at least 22 weeks of gestation. "Genes TBC1D17 associated with sire calving ease, and CRACR2B associated with sire stillbirth, were also identified (P < 0.05)." (PMID 38711039, 2024).
tumor (3 papers, 2020 to 2024). "Possibly, MyoMed-946, in contrast to MyoMed-205, rapidly affects dividing tumor cells via Ttll12 and Tbc1d17, a hypothesis that has to be validated in future studies." (PMID 33050629, 2020).
TBC1D17 also shares sentences with these, for which no sentence is quoted: cancer (2 papers); cervical cancer (1); glioblastoma (1); glioma (1); skin cutaneous melanoma (1).